IGF1 (insulin like growth factor 1)
Diseases named in the same sentence as IGF1 in open-access papers (continued):
Sharing a sentence is not in itself a finding about the gene and the disease.
synovitis (3 papers, 2014 to 2023). Inflammation of a synovial membrane. "Still, the differentially expressed level of insulin-like growth factor 1 in the synovium of OA was first mentioned in this study and might be a new therapeutic target in synovitis in early-stage OA." (PMID 37545537, 2023). "Similarly, we did not observe any difference in IGF-1 or IGFBP-3 levels when patients were stratified according to history of anterior uveitis, presence of syndesmophytes, hip involvement or synovitis in other peripheral joints, peripheral enthesitis, and HLA-B27 status (data not shown)." (PMID 25295265, 2014).
systemic lupus erythematosus (3 papers, 2004 to 2025). An autoimmune multi-organ disease typically associated with vasculopathy and autoantibody production. "This study was designed to compare basal serum growth hormone, insulin-like growth factor-1 and somatostatin levels in female systemic lupus erythematosus patients to a group of normal female subjects." (PMID 15496230, 2004). "Previous studies suggested that defects in the hypothalamic/pituitary axis contributed to systemic lupus erythematosus disease progression which could also involve growth hormone, insulin-like growth factor-1 and somatostatin function." (PMID 15496230, 2004). "Serum insulin-like growth factor-1 levels were significantly elevated (p < 0.001) in systemic lupus erythematosus patients, but only when compared to the entire group of normal subjects." (PMID 15496230, 2004).
tauopathy (3 papers, 2018 to 2025). Neurodegenerative disorders involving deposition of abnormal tau protein isoforms (tau proteins) in neurons and glial cells in the brain. "IGF-1 plays a major role in regulating tau phosphorylation in the aging brain, and insulin- or IGF-1-activated PI3K/Akt/GSK-3β signaling may be involved in several tauopathies." (PMID 31093272, 2019).
temporal lobe epilepsy (3 papers, 2017 to 2020). A localization-related (focal) form of epilepsy characterized by recurrent seizures that arise from foci within the temporal lobe, most commonly from its mesial aspect. "Increasing neurogenesis after TBI has been suggested to enhance the likelihood of seizure activity; however, IGF1 treatment has been shown to reduce seizure behavior in a rodent model of temporal lobe epilepsy." (PMID 32276671, 2020). "Serum levels of IGF-1 in patients with temporal lobe epilepsy were significantly lower than those in patients with extratemporal lobe epilepsy." (PMID 30524358, 2018).
thymic atrophy (3 papers, 2009 to 2026). "IGF-1 also regenerates the thymus in a rat model of dexamethasone-induced thymic atrophy." (PMID 19479077, 2009).
Tinnitus (3 papers, 2022 to 2023). Tinnitus is an auditory perception that can be described as the experience of sound, in the ear or in the head, in the absence of external acoustic stimulation. "While we observed correlations of IL-1b, TNF-α, and IGF-1 with tinnitus loudness, these associations did not persist in network analysis." (PMID 35814090, 2022). "The first network included tinnitus loudness (SL) and correlated blood parameters (TNF-α, IL-1b, IGF-1) and their covariates (age, hearing threshold, systolic blood pressure, LDL cholesterol, VEGF, non-classical monocytes, intermediate monocytes)." (PMID 35814090, 2022).
Urinary incontinence (3 papers, 2016 to 2025). Loss of the ability to control the urinary bladder leading to involuntary urination. "Serum IGF‐1 levels were measured preoperatively, and their association with wound healing, inflammatory cytokines, and postoperative anal function was analyzed using logistic regression, receiver operating characteristic (ROC) analysis, and Wexner Incontinence Score." (PMID 41199981, 2025). "A clinical study on urinary incontinence by Ozbek et al20 showed that the expression of IGF-1 was decreased in the serum of patients with urinary incontinence." (PMID 34432732, 2021). "Another basic study by Sumino et al21 showed that the expression of IGF-1 was decreased in the transverse striated sphincter of the urinary tract in mice with incontinence." (PMID 34432732, 2021). "Patients with serum IGF‐1 levels above this threshold experienced fewer complications, including lower rates of inflammation (redness, swelling, fluid accumulation), and demonstrated improved postoperative anal function as indicated by lower Wexner incontinence scores." (PMID 41199981, 2025).
uveal melanoma (3 papers, 2016 to 2024). A melanoma derived from melanocytes of the uveal tract. "In addition, we found elevated IGF1 mRNA expression in BAP1-mutant uveal melanomas, where higher expression levels are associated with a poorer prognosis." (PMID 38969833, 2024). "A study on uveal melanoma supports the role of exogenous and endogenous IGF-1 and their interaction with IFG-1R in the development of metastases in the liver, which is a major site for IGF-1 production and the predominant metastatic site in 70-90% of uveal melanoma." (PMID 27102439, 2016).
acquired hypopituitarism (2 papers, 2014). "In contrast to acquired hypopituitarism cases, congenital severe GHD cases have much lower serum IGF1 levels and have never been exposed to GH and thus they may not be equivalent in terms of GH/IGF1 axis disturbances and health prognosis." (PMID 24683479, 2014).
acute lung injury (2 papers, 2020 to 2021). A condition of lung damage that is characterized by bilateral pulmonary infiltrates (pulmonary edema) rich in neutrophils, and in the absence of clinical heart failure. "In this study, we demonstrated that IGF-1 was upregulated in BALF and lung tissues of acute lung injury (ALI) mice, and that the increased IGF-1 was mainly derived from AMs." (PMID 32793225, 2020).
adolescent idiopathic scoliosis (2 papers, 2015 to 2023). A scoliosis with no known cause arising in adolescent. "The irregular expression of growth hormone and insulin-like growth factor-1 (IGF-1) may disturb hormone metabolism, result in a gross asymmetry, and promote the progress of adolescent idiopathic scoliosis." (PMID 26380113, 2015).
adrenal tumor (2 papers, 2021 to 2024). "Given that our patient had normal IGF-1 levels, there could be a different underlying mechanism that contributed to the concomitant occurrence of CM1 with the pituitary and adrenal tumors." (PMID 38919912, 2024).
alopecia areata (2 papers, 2025). Loss of scalp and body hair involving microscopically inflammatory patchy areas. "It is proposed that IGF-1, an agent that preserves immune privilege in anagen hair follicles in alopecia areata, also stimulates the regeneration rate of hair follicle cells." (PMID 40416990, 2025).
alveolar rhabdomyosarcoma (2 papers, 2013 to 2018). A rapidly growing malignant mesenchymal neoplasm. "The roles of IGF-1 signaling are also documented in patients with pneumothorax and alveolar rhabdomyosarcoma (ARMS), in animal models of pulmonary artery hypertension and postpneumonectomy lung regeneration." (PMID 30018981, 2018).
aromatase deficiency (2 papers, 2015 to 2021). Aromatase deficiency disrupts the synthesis of estradiol, resulting in hirsutism of mothers during gestation of an affected child; pseudohermaphroditism and virilization in women; and tall stature, osteoporosis and obesity in men. "A study of men with congenital aromatase deficiency indicated that estradiol regulates the production of IGF1." (PMID 33731067, 2021). "However, longitudinal bone growth might occur and progress also independently from the GH/IGF-1 status but at a lower rate since men with aromatase deficiency continue to slowly increase their stature during adulthood, despite severe GH deficiency." (PMID 25873947, 2015). "The fact that estrogen replacement treatment was effective on epiphyseal closure and growth arrest in all patients with aromatase deficiency, despite insufficient GH and IGF-1 production, implies that GH and IGF-1 do not play a major role in the process of growth plate closure in humans." (PMID 25873947, 2015).
asthenia (2 papers, 2018). Clinical sign or symptom manifested as debility, or lack or loss of strength and energy. "IGF-1 measurements at 12 months showed a consistent mean increase from 46.5±31μg/L to 134.3±86 μg/L and three patients referred improvement of asthenia and stress tolerance." (PMID 30356378, 2018).
Barth syndrome (2 papers, 2012 to 2021). Barth syndrome (BTHS) is an inborn error of phospholipid metabolism characterized by dilated cardiomyopathy (DCM), skeletal myopathy, neutropenia, growth delay and organic aciduria. "Higher levels of IL-6 and lower IGF-1 levels were observed in Barth syndrome patients compared with age-matched controls." (PMID 33001359, 2021). "Furthermore, lower levels of IGF-1 may contribute to some of the growth delays and myopathies observed in Barth Syndrome." (PMID 22721508, 2012).
biliary atresia (2 papers, 2013 to 2018). A rare, biliary tract disease characterized by progressive obliterative cholangiopathy of the intra- and extrahepatic bile ducts, occurring in the embryonic/ perinatal period, leading to severe and persistent neonatal jaundice and acholic stool. "For biliary atresia, a recent report identified miR-29a to be increased in the livers of neonatal mice subjected to a similar RRV infection protocol, and to target the Igf1 and Il1rap genes in vivo." (PMID 24138927, 2013).
bone metabolic disorders (2 papers, 2025 to 2026). "As IGF-1 and growth hormone levels decrease with age, bone metabolic disorders and OP become more likely, increasing fracture risk." (PMID 41601928, 2026).
bone metastasis (2 papers, 2013 to 2023). Transfer of a neoplasm from its primary site to bones. "Polymorphisms of the IGF-1 especially C-T haplotype are associated with worse survival of PCa patients with bone metastasis at initial diagnosis and may be a novel predictor in PCa patients with bone metastasis." (PMID 36831629, 2023).
brain hemorrhage (2 papers, 2014 to 2020). "Indeed, one study showed that the presence of Igf1, the ligand for Igf1r, resulted in improved BBB integrity following brain hemorrhage." (PMID 32843537, 2020). "Although IGF1 level was lower in patients with intracranial haemorrhage, it was not significant." (PMID 24523937, 2014).
breast disease (2 papers, 1992 to 2010). "Studies on genetic variants of IGF2 in relation to breast disease are few, and to our knowledge, the present study is the first to look at IGF2 polymorphisms in relation to levels of mammographic density, IGF1 and IGFBP3." (PMID 20302654, 2010). "To assess the precise role of IGF1 in benign and malignant breast diseases, we analysed the tissular localisation, characterised, and quantified specific insulin-like growth factor 1 (IGF1) binding sites in these heterogenous tissues, using histo-autoradiographic analysis (HAA)." (PMID 1323990, 1992).
bronchiectasis (2 papers, 2018 to 2024). Segmental, irreversible dilation of the bronchial tree resulting in the accumulation of secretions which leads to obstruction. "Third, because serum GH or IGF-1 level was unavailable in claims data, GH or IGF-1 level could not be compared between patients with or without bronchiectasis." (PMID 39220366, 2024). "There are concerns that IGF-1 might have roles in non-CF bronchiectasis like in CF." (PMID 30018981, 2018). "Therefore, although the role of IGF-1 cannot be proven in situations where exact values ​​of IGF-1 levels are not available, it can be hypothesized that high IGF-1 levels may be qualitatively, if not quantitatively, involved in the development of bronchiectasis." (PMID 39220366, 2024).
calcification (2 papers, 2020 to 2024). Process by which organic tissue becomes hardened by the physiologic deposit of calcium salts. "His insulin-like growth factor 1 (IGF-1) level was reduced at 11.6 nmol/L (8.9 μg/dL) (13-40 nmol/L [9.9-30.6 μg/dL]) and he also had TSH resistance and extensive intracranial calcifications." (PMID 39193092, 2024).
carcinoma in situ (2 papers, 2020 to 2024). "In urinary bladder cancer, carcinoma in situ and normal urothelium expression of all three IGF1 mRNAs has been observed (Ea, Eb i Ec)." (PMID 32977489, 2020). "Significant downregulation of IGF1Ec isoform expression was reported in cancer, compared to normal urothelium, while increased expression of all IGF1 mRNAs were observed in in situ carcinomas." (PMID 32977489, 2020).
cerebral microbleeds (2 papers, 2023 to 2026). Cerebral microbleeds are a group of pathological processes affecting the small arteries, arterioles, capillaries and venules of the brain, as detected by brain imaging techniques. "There are many similarities between cerebral microbleeds (CMBs) observed in IGF-1-deficient mice and in elderly hypertensive patients, including the relative size of the hemorrhage, clinical signs, and progressive nature of the pathological process." (PMID 37358957, 2023).
Chagas disease (2 papers, 2022 to 2023). A parasitic infection caused by Trypanosoma cruzi. "IGF-1 has been demonstrated to reduce inflammation levels in chronic experimental Chagas disease." (PMID 35457151, 2022). "In the current ex vivo study, we employed serum from GHR-/- mice, also known as LS mice (a model of GH resistance with high GH and low IGF-1 levels), and serum from bovine GH (bGH) transgenic mice (high GH and IGF-1), to test the effect on Trypanosoma cruzi infection." (PMID 37163287, 2023).
chronic bronchitis (2 papers, 2009 to 2018). A type of chronic obstructive pulmonary disease characterized by chronic inflammation in the bronchial tree that results in edema, mucus production, obstruction, and reduced airflow to and from the lung alveoli. "Colocalization of IGF-1 and Bcl-2 is induced in airway epithelial cells by cigarette smoking in mice or is observed in lung tissues from patients with chronic bronchitis." (PMID 30018981, 2018). "Emphysematous patients seem to have significantly lower IGF-1 levels compared to those with chronic bronchitis both on admission and at discharge." (PMID 30018981, 2018).
colon adenoma (2 papers, 2009 to 2018). An adenoma that arises from the colon. "The present study explored serum adiponectin, leptin, IGF-1, and TNF-α association with colon adenoma." (PMID 29593647, 2018).
complication (2 papers, 2017). Any disease or disorder that occurs during the course of, or because of, another disease, treatment, or procedure. "The greater angiogenic potential of T2DM–BMMSCs secretome may reflect the interactive actions of multiple bioactive mediators (including IGF‐1, LTBP1 and LTBP2) which may alter the functions of endothelial cells, key players in diabetic vascular complications." (PMID 27641937, 2017).
cryptococcal infections (2 papers, 2022). "Here, we showed that defects in C. elegans insulin/insulin-like growth factor-1 (IGF-1) signaling (IIS) pathway influenced animal lifespan and mechanisms of host resistance in cryptococcal infections, which required the activation of aging regulator DAF-16/Forkhead box O transcription factor." (PMID 35733100, 2022).
diabetic encephalopathy (2 papers, 2014 to 2015). A brain disease that is characterized by functional impairment of cognition, cerebral signal conduction, neurotransmission and synaptic plasticity, and underlying structural pathology associated with diabetes. "However, because insulin can cross-activate the insulin-like growth factor type 1 receptor (IGF-1R), which also functions in most of tissues, such as muscle and bone, it has been difficult to establish the direct (IGF-1-independent) actions of insulin in the pathogenesis of diabetic encephalopathy." (PMID 26089889, 2015).
diabetic ketoacidosis (2 papers, 2010 to 2024). The metabolic condition resulted from uncontrolled diabetes mellitus, in which the shift of acid-base status of the body toward the acid side because of loss of base or retention of acids other than carbonic acid is accompanied by the accumulation of ketone bodies in body tissues and fluids. "In severe insulin deficiency, for example in diabetic ketoacidosis, IGFBP-1 is upregulated while hepatic IGF-1 secretion is reduced, despite increased GH." (PMID 20723227, 2010).
dry eye (2 papers, 2020 to 2024). "Topical insulin has been reported to improve dry eye symptoms in diabetic patients, inducing IGF-1-mediated corneal nerve regeneration and corneal epithelial proliferation." (PMID 38744994, 2024).
embryonal carcinoma (2 papers, 2013 to 2015). A non-seminomatous malignant germ cell tumor characterized by the presence of large germ cells with abundant cytoplasm resembling epithelial cells, geographic necrosis, high mitotic activity, and pseudoglandular and pseudopapillary structures formation. "Moreover, TGF-β inhibited migration in C2Cl2 skeletal muscle satellite cell and P19 embryonal carcinoma cell via decreasing IGF-1." (PMID 26106417, 2015).
erythrocytosis (2 papers, 2010 to 2020). "There are numerous other possible etiologies for polycythemia, including mutations in PHD enzymes, VHL proteins, alterations in angiotensin II signaling, upregulation of insulin-like growth factor-1 signaling, and constitutive activation of the JAK/STAT pathway." (PMID 32235007, 2020).
Exotropia (2 papers, 2016 to 2020). A form of strabismus with one or both eyes deviated outward. "The common pattern of change in eye alignment over time after sustained IGF-1 or GDNF treatment was a slight decrease in exotropia in the first two weeks followed by maintenance of misalignment for the duration of treatment." (PMID 32681083, 2020). "This study demonstrates that in adult nonhuman primates with a sensory-induced exotropia in infancy, continuous IGF-1 treatment improves eye alignment, resulting in muscle fiber enlargement and altered innervational density that includes the untreated muscles." (PMID 27820875, 2016).
focal epilepsy (2 papers, 2018 to 2021). A seizure caused by a localized disorder. "Our previous study showed that perturbed brain-derived neurotrophic factor and insulin-like growth factor 1 signaling in the central autonomic system contribute to autonomic dysfunction and impaired cerebral autoregulation in patients with focal epilepsy." (PMID 33920691, 2021).
Gait ataxia (2 papers, 2014). A type of ataxia characterized by the impairment of the ability to coordinate the movements required for normal walking. "Exogenous trophic factors (such as glial derived neurotrophic factor and IGF-1) can delay the onset of hereditary Purkinje cell degeneration and gait ataxia in shaker mutant rats." (PMID 26331037, 2014). "Exogenous trophic factors (GDNF and/or IGF-1) can delay the onset of hereditary Purkinje cell degeneration and gait ataxia in shaker mutant rats characterised by spatially restricted degeneration of cerebellar Purkinje neurons from adult-onset heredodegeneration." (PMID 26331034, 2014).
Giardia infection (2 papers, 2021 to 2025). "We found that Giardia infection was negatively associated with length-for-age and Insulin-like Growth Factor 1 (IGF-1) levels, positively associated with biomarkers of intestinal epithelial disruption, yet uncoupled from markers of systemic inflammation and intestinal inflammation." (PMID 41292641, 2025). "Our study also provided evidence that Giardia infection is negatively associated with LAZ, markers of chronic intestinal damage, and IGF-1 and positively associated with markers of intestinal epithelial disruption." (PMID 41292641, 2025). "While IGF-1 is a well-recognized hormonal driver of linear growth, its relationship with Giardia infection has not been previously explored." (PMID 41292641, 2025).
glomerular diseases (2 papers, 2018 to 2024). "Corticosteroids are effective drugs for some glomerular diseases, but, may adversely affect linear growth by a variety of mechanisms, including reduced pulsatile secretion of GH, impaired sensitivity of the GH receptor to IGF-1, and decreased production of IGF-1." (PMID 30155452, 2018).